SHBG (sex hormone binding globulin)
Diseases named in the same sentence as SHBG in open-access papers (continued):
Sharing a sentence is not in itself a finding about the gene and the disease.
cancer (continued). "We recently found that serum SHBG and SHBG mRNA levels are low when the hepatic triglyceride concentration is elevated in a study of adult men and women undergoing hepatic resection as treatment for cancer." (PMID 26761949, 2016). "A direct correlation between hepatic HNF4-α and SHBG mRNA levels has been also observed in cancer patients, in whom hepatic HNF4-α and SHBG mRNA levels were reported to be inversely related to hepatic triglyceride levels and to decrease in relation to body mass index." (PMID 27113851, 2016). "There are reports that plasma SHBG may play a role in the development of several sex hormone-related carcinomas, e.g. breast, prostate and ovarian carcinomas." (PMID 24386165, 2013). "Thus, our findings are consistent with the previous reports on the potential role of intracellular SHBG in other hormone-targeting carcinomas." (PMID 24386165, 2013). "At the same time, they also raise many new and important questions, including the viability of novel alternatively spliced transcripts, their functions in hormonally responsive tissues, including the breast and prostate, and the role that aberrant SHBG gene expression may play in cancer." (PMID 19416531, 2009). "Our mediation analysis with clinical biomarkers for CVD and cancer revealed that CRP and SHBG partially medicated the effects of the omega-6/omega-3 ratio on all-cause mortality." (PMID 38578269, 2024). "High levels of physical activity can regulate sex hormone levels by increasing levels of sex hormone-binding globulin (SHBG), ultimately reducing the incidence of cancer." (PMID 36510257, 2022). "In addition to the extensive allelic heterogeneity at the SHBG locus, our data identify loci with a role in sex steroid hormone metabolism, which may help elucidate the role of sex steroid hormones in disease, particularly T2D and hormone-sensitive cancers." (PMID 22829776, 2012). "Our exclusion criteria ensured absence of confounding factors such as cancer, oophorectomy/hysterectomy, and hormone therapy use, paired with correction for age and SHBG levels." (PMID 40773017, 2026). "Further translational studies are warranted to determine whether SHBG normalisation may serve as both a biomarker and a mediator of therapeutic response in KMT-treated cancer patients." (PMID 41586225, 2025). "Although our MR‐PheWAS of the phecodes did not identify a significant association with any cancers, the biomarker analyses found an association between HMGCR (statin proxy) and lower levels of testosterone and SHBG." (PMID 37208559, 2023). "SHBG expression has also been demonstrated in sex hormone target tissues such as human prostate, LNCaP cells, testes, duodenum, ovary, placenta, proximal tubule epithelial cells (PTEC), and cerebral cortex as well as several cancers." (PMID 27990161, 2016). "Besides SHBG has been previously studied for its effect on various cancer cell lines growth and survival, its influence on non-cancerous cells proliferation and viability has not yet been elucidated." (PMID 37402098, 2023). "For the cancer related traits, a negative correlation was observed between hormone-sensitive cancers and oestradiol level (rp = −0.0190, se = 0.0022, P = 2.20E-16); SHBG (rp = −0.0059, se = 0.0022, P = 7.35E-03)." (PMID 35729236, 2022). "In fact, hyperinsulinemia can contribute to the genesis of cancer, as binding to circulating IGF binding proteins and sex hormone binding globulins (SHBG) increases the bioavailability of IGF-1 and sex hormones, which may play a decisive role in cell proliferation." (PMID 35743815, 2022). "Effects of SHBG on other cancers in women have not been systematically examined." (PMID 34187478, 2021). "There is consistent epidemiological evidence that the hormones insulin-like growth factor-I (IGF-I), sex hormone-binding globulin (SHBG: this molecule is not a hormone, but modifies sex hormone activity), and total and free testosterone may be related to cancer risk." (PMID 34216337, 2021).
cancer (continued). "The role of SHBG in NPC remains unclear and largely unexplored, as NPC is not typically considered a hormone-driven cancer." (PMID 40565234, 2025).
metabolic disorders (54 papers, 2013 to 2026). "Due to the close correlation between metabolic disorders, an attempt was made to assess the usefulness of SHBG assessment as a risk marker for MS, DM2, and cardiovascular incidents." (PMID 40427034, 2025). "It is noteworthy that some studies have demonstrated an association of SHBG with metabolic disorders and low-grade inflammation in patients with PCOS." (PMID 41300953, 2025). "Over the past few decades, low SHBG levels have consistently been linked to an increased risk of developing various metabolic disorders." (PMID 40495241, 2025). "Further large-scale prospective investigations are warranted to substantiate the role of SHBG as a routine clinical biomarker and to evaluate its potential incorporation into diagnostic panels for endocrine and metabolic disorders." (PMID 40427034, 2025). "Higher SHBG levels have been implicated in a variety of conditions, including cardiovascular disease and metabolic disorders." (PMID 39759528, 2024). "Recent studies have indicated that lower SHBG and TT levels are significantly associated with an increased risk of developing metabolic disorders." (PMID 38988998, 2024). "In men, it has been recently shown that SHBG, independently of T, is associated with worse lipid profile and blood pressure, thus supporting the value of SHBG as a pure marker of metabolic disorders." (PMID 33854482, 2021). "An association has also been described between SHBG actions unrelated to the transport of sex hormones and metabolic disorders." (PMID 34335746, 2021). "Several cross-sectional and cohort studies have shown that low SHBG levels are associated with an increased risk of developing metabolic diseases." (PMID 34335746, 2021). "Evaluation of gonadal hormones and SHBG may help provide risk stratification strategies or novel therapies to prevent or treat metabolic disorders." (PMID 38988998, 2024). "Importantly, circulating SHBG levels are strongly correlated with plasma testosterone concentrations and low testosterone levels are strongly associated with metabolic disorders." (PMID 34335746, 2021). "According to our results, hyperandrogenic components per se (TT, FAI, and SHBG) could be predictors of metabolic disorders and thus increased risk of MetS." (PMID 32494764, 2020). "This needs to be explored in futureinvestigations, including the use of SHBG as a possible biomarker or predictor ofchronic metabolic diseases and unfavorable cardiovascular outcomes." (PMID 40857627, 2025). "Given the strong association between SHBG levels and MetS and T2DM, as well as evidence that genetic-raising alleles lower risk for these metabolic disorders, some authors have proposed a role for SHBG in the pathogenesis of IR and T2DM." (PMID 40863113, 2025). "Our study advances knowledge in the field by linking SHBG levels, BMI, and blood pressure to fatty liver and metabolic health, with implications for clinical practice and further research on metabolic disorders." (PMID 39768643, 2024). "Sex hormone binding globulin (SHBG) is a glycoprotein synthesized in the liver and has been found to be associated with metabolic disorders." (PMID 37334312, 2023). "The role of SHBG as a mediator and a biomarker for metabolic disease, independently of androgens, was recently discovered with Mendelian randomization in GWAS studies." (PMID 37685811, 2023). "SHBG and a plethora of other hepatokines are believed to function equally as mediators and biomarkers for metabolic diseases." (PMID 37685811, 2023). "It is increasingly recognized that SHBG, which is produced by the liver, is involved in the development of metabolic disorders." (PMID 36675601, 2023). "To date, in fact, several studies have demonstrated how SHBG also represents a biomarker of metabolic disorders, such as de novo lipogenesis." (PMID 36235799, 2022). "This condition is also exacerbated by the reduction in SHBG, which is currently considered a biomarker of metabolic disorders, in particular T2DM." (PMID 36235799, 2022).
metabolic disorders (continued). "Both PCOS and T2DM are also consequences of lower serum sex-hormone-binding globulin (SHBG) levels, which is currently considered a biomarker of metabolic disorders, in particular T2DM." (PMID 36235799, 2022). "Therefore, cardiac SHBG expression may be associated with intracardiomyocyte testosterone signaling, allowing cardioprotective effects or, otherwise, producing cardiac dysfunction under metabolic disorder conditions." (PMID 34335746, 2021). "In the presented study, we also investigated the expression of two novel biomarkers of metabolic disorders—fetuin-A and SHBG." (PMID 33536069, 2021). "Recently, sex hormone-binding globulin (SHBG), a glycoprotein with a molecular mass about 90 kDa that is primarily synthesized in the liver, has been implicated in the development of metabolic disorders." (PMID 33808055, 2021). "In conclusion, lower serum SHBG is associated with a higher prevalence of NAFLD, compared with MS and other metabolic disorders, in T2D patients." (PMID 29109457, 2017). "Lower serum SHBG is more associated with a higher prevalence of NAFLD, compared with MS and other metabolic disorders." (PMID 29109457, 2017). "However, more studies on larger groups of patients with metabolic disorders, diverse in terms of age and gender, should be performed to establish the exact usefulness of SHBG." (PMID 40427034, 2025). "Overall, these provocative but conflicting studies await confirmation, and the notion that SHBG exerts steroid-independent metabolic effects such that SHBG analogs might represent a novel treatment for metabolic disorders remains preliminary." (PMID 40863113, 2025). "SHBG serum level is strongly correlated with metabolic diseases." (PMID 40427034, 2025). "Our study revealed that Pb exposure had linear positive association with SHBG in the adjusted models, which was apparent in nearly all subgroups except in normal BMI group, thus influencing the utility of SHBG as a sensitive biomarker of the degree of inflammation in metabolic diseases." (PMID 37534216, 2023). "Therefore, increased DHEA-S and SHBG levels caused by regular aquatic exercise should help to prevent CVD and reduce risk for metabolic diseases in women aged 70–82 years." (PMID 33918160, 2021). "Although metabolic disorders increase the incidence of cardiovascular disease, it is unclear whether SHBG expression has an impact on SHBG receptor signaling or androgen actions in cardiac cells." (PMID 34335746, 2021). "Meanwhile, plasma SHBG has been applied to clinical examinations of various metabolic diseases." (PMID 33104518, 2020). "Hence, SHBG, as well as testosterone among men may decrease PAI1 levels, and thereby positively influence the risk of developing CVD, metabolic disorders, and inflammation." (PMID 37369886, 2024). "The relationship between SHBG and metabolic disorder might be explained by androgen." (PMID 33101409, 2020). "Second, SHBG itself might contribute to the development of metabolic disorders." (PMID 30455723, 2018). "Moreover, SHBG could also serve as a biomarker of the degree of inflammation in metabolic diseases." (PMID 37534216, 2023). "Other studies confirmed the relationship between the concentration of testosterone, DHEA-S, and SHBG and the pathophysiology of PCOS and metabolic disorders." (PMID 32967289, 2020). "Elevated sex hormone–binding globulin (SHBG) levels have been observed in the setting of HIV and may protect against some metabolic disorders." (PMID 32128321, 2019). "Past research on the relationships between SHBG and NAFLD has often been performed in patients with metabolic disorders, and the results showed that serum SHBG levels were lower in NAFLD patients with metabolic disorders than in those without NAFLD." (PMID 30455723, 2018). "Visceral adiposity has been particularly related with reduction of T and SHBG levels (independent of other metabolic disorders)." (PMID 24459467, 2013).
metabolic disorders (continued). "Overall, the obtained data clearly demonstrate the benefice of SHBG treatment in the regulation of adipose tissue metabolism in the course of EMS and provide new insights for the development of molecular therapies with potential translational application to human metabolic disorders." (PMID 38146533, 2023). "Hence, SHBG <33.4 nmol/L is an effective marker for identifying women with altered metabolic parameters and higher NAFLD risk in either high risk groups, such as those with PCOS, or those consulting for conditions not directly linked to metabolic disease, such as female sexual dysfunction." (PMID 33854482, 2021). "The insulin-responsive gene sex hormone-binding globulin (SHBG) links hyperinsulinaemia and altered testosterone concentrations in humans, with genetic studies suggesting a bidirectional relationship between SHBG and metabolic disease, yet no orthologue circulates in mouse plasma." (PMID 34841432, 2021).
cardiovascular disease (53 papers, 2010 to 2025). "First, we assessed the causality between serum SHBG levels and five cardiovascular diseases using univariable MR." (PMID 38796576, 2024). "High androgen concentration and low SHBG concentration are associated with cardiovascular disease risk factors after menopause." (PMID 38650726, 2024). "Epidemiological studies have shown that low SHBG plasma levels are a risk factor for developing cardiovascular disease." (PMID 35572853, 2022). "Another cohort study showed, in a group with age ranging from 35 to 80 years, that elevated levels in SHBG were positively associated with increased incidental cardiovascular disease risk in men over 65 years." (PMID 34335746, 2021). "The effect of insulin on the SHBG production is of particular interest as low SHBG levels can, in part, predict the development of T2D and are associated with increased risk of cardiovascular disease and death." (PMID 23781314, 2013). "Interestingly, olive oil is one of the main components of the Mediterranean diet and SHBG levels were associated with a lower risk of cardiovascular disease." (PMID 33514384, 2021). "In addition, low SHBG is associated with a greater coronary artery calcium score and increased risk for cardiovascular disease (CVD) in post-menopausal women." (PMID 33139661, 2020). "The beneficial effects of SHBG on cardiovascular disease events in men is so far unproven, however, data on 2563 community-dwelling men (35 to 80 years) showed that elevated SHBG was associated with both a greater risk of CVD and an increased CVD mortality among all men and men > 65 years." (PMID 33139661, 2020). "Therefore, RES may improve glucose metabolism and reduce the risk of cardiovascular diseases in DKD patients by targeting SHBG." (PMID 37308949, 2023). "In reproductive-aged women without PCOS, SHBG levels, but not total or free testosterone levels, were inversely associated with subclinical cardiovascular disease assessed by coronary artery calcified plaques and carotid artery intima-media thickness." (PMID 25024746, 2014). "By contrast, we have analyzed the possible effect of this SNP over serum SHBG and FT in a homogenous sample population, with no interferences concerning ageing, or the presence of T2D or cardiovascular disease, comorbidities frequently associated in the obese male." (PMID 31370189, 2019). "Better knowledge of factors controlling the production of SHBG is important not least because of strong evidence for the relationship between SHBG and cardiovascular disease." (PMID 23781314, 2013). "We found that bioavailable testosterone levels were directly correlated to plasma BDNF levels in males, and the opposite occurred for SHBG, indicating that plasma BDNF could play a role in the pathogenesis of metabolic and cardiovascular disorders in male hypogonadism." (PMID 20404913, 2010). "Population-based study of total testosterone, sex hormone binding globulin (SHBG), triglycerides (TG), total cholesterol and high-density lipoprotein (HDL) was analyzed in 1274 men without known cardiovascular disease." (PMID 39286801, 2024).